FXYD5 (FXYD domain containing ion transport regulator 5)
Description:
Associates with and regulates the activity of the sodium/potassium-transporting ATPase (NKA) which catalyzes the hydrolysis of ATP coupled with the exchange of Na(+) and K(+) ions across the plasma membrane (By similarity). May increase NKA activity by increasing the apparent affinity for Na(+). Involved in down-regulation of E-cadherin which results in reduced cell adhesion. Promotes metastasis.
Synonyms: DYSAD; IWU1; HSPC113; OIT2; KCT1; PRO6241; RIC
Tractability: Antibody: UniProt places it where antibodies can reach, with high confidence; its Gene Ontology location is reachable by antibodies, with high confidence; UniProt predicts a signal peptide or a membrane-spanning region. PROTAC: ubiquitination databases record sites on it.
Gene: Protein-coding gene on chromosome 19 (35,154,569 to 35,171,791, forward strand). Ensembl gene ENSG00000089327.
Subcellular location: Cell membrane; Basolateral cell membrane
Subcellular location (Human Protein Atlas): Endoplasmic reticulum
Gene Ontology:
Molecular function: actin binding; cadherin binding; protein binding; sodium channel regulator activity; ion channel regulator activity
Biological process: establishment or maintenance of transmembrane electrochemical gradient; intracellular potassium ion homeostasis; intracellular sodium ion homeostasis; microvillus assembly; negative regulation of calcium-dependent cell-cell adhesion; positive regulation of sodium ion export across plasma membrane; potassium ion import across plasma membrane; proton transmembrane transport; sodium ion export across plasma membrane; regulation of monoatomic ion transport
Cellular component: membrane; plasma membrane; basolateral plasma membrane
Genetic constraint (gnomAD): Loss-of-function variants: 6 observed, 10.44 expected, observed/expected ratio (o/e) 0.58, 90% interval 0.31 to 1.13. The upper end of that interval is the gene's LOEUF score, 1.13, which puts it in group 4 of 6, group 1 being the genes least tolerant of losing a copy. Missense variants: 127 observed, 126.98 expected, observed/expected ratio (o/e) 1, 90% interval 0.87 to 1.16. Synonymous variants: 56 observed, 52.64 expected, observed/expected ratio (o/e) 1.06, 90% interval 0.86 to 1.33.
Homologues: Paralogues in human: FXYD1 (13% identical), FXYD3 (13% identical), FXYD4 (13% identical), FXYD6 (13% identical), FXYD2 (12% identical), FXYD7 (10% identical).
Diseases named in the same sentence as FXYD5 in open-access papers:
FXYD5 is named in the same sentence as 37 diseases in open-access papers, as found by Europe PMC text mining. Sharing a sentence is not in itself a finding about the gene and the disease. The quoted sentences say what the papers report.
breast carcinoma (8 papers, 2016 to 2024). "In addition, more global, molecular changes were found to be associated with FXYD5 overexpression in breast cancer model." (PMID 27066483, 2016). "The peptide is, at least in part, expected to be a functional equivalent of FXYD5, and FXYD5 expression increases the metastatic potential in a mouse breast cancer model." (PMID 35371992, 2022). "FXYD5 stimulated the invasion and metastasis of breast cancer cells, and patients with high FXYD5 expression suffered from a lower complete remission rate after receiving RT for head and neck cancer." (PMID 34270462, 2021). "Studies done in breast cancer tissues showed a positive FXYD5/Dys immunostaining where cell–cell contacts had been lost." (PMID 31867269, 2019). "Previous studies in breast cancer cells have demonstrated that FXYD5 knockdown decreases, while FXYD5 overexpression increases, both the NF-κB-responsive promoter activity and CCL2 production in cancer cells." (PMID 28620381, 2017). "A study, using a global gene expression analysis approach, identified chemokine (C-C motif) ligand 2 (CCL2) as the transcript most effected by silencing FXYD5 in MDA-MB-231 breast cancer cells." (PMID 27066483, 2016). "Furthermore, in breast cancer cell lines, high FXYD5 expression correlates with activation of AKT signalling, which drives the EMT60." (PMID 34059618, 2021). "This conclusion is consistent with previously published data showing that FXYD5 overexpression in breast cancer cells induces the phosphorylation of AKT, which promotes the transcriptional activity of NF-κB-responsive promoter elements and increases levels of CCL2 mRNA." (PMID 28620381, 2017). "The presence of FXYD5 was also accompanied by increased activation of AKT, demonstrated by elevated abundance of phospho-AKT in breast cancer tumors." (PMID 27066483, 2016).
ovarian carcinoma (7 papers, 2019 to 2024). A malignant neoplasm originating from the surface ovarian epithelium. "Our study showed an association between FXYD5 overexpression and carboplatin resistance in ovarian cancer." (PMID 31434988, 2019). "The increase in FXYD5 expression was less after treatment of fibroblasts with exosomes derived from drug-treated ovarian cancer cell lines tested (both SKOV-3 and TOV-21G)." (PMID 36012171, 2022). "Analysis of the expression of the FXYD5 gene (FXYD domain-containing ion transport regulator 5) showed, in most cases, an increase in the expression of this gene after treatment of fibroblasts with exosomes derived from ovarian cancer cells." (PMID 36012171, 2022). "When we analysed FXYD5 CNV in cancer cell lines available in the Cancer Cell Lines Encyclopedia (CCLE) Database of the Broad Institute, we found that FXYD5 showed a general higher CNV score in ovarian cancer cell lines than all others tumour types." (PMID 31434988, 2019). "Similarly, biological experiments in vitro and in vivo showed that FXYD5 promoted the metastasis of ovarian cancer cells via TGF-β/SMAD signaling pathways." (PMID 32596316, 2020). "TGFB1 is positively regulated by a feedback loop involving FXYD5, TGF β/SMADs signaling drives EMT during ovarian cancer progression." (PMID 38031074, 2023). "In ovarian cancer, the TGF-β-activated SMAD3/SMAD4 complex is recruited to the promoter region of FXYD5 and promotes FXYD5 transcription." (PMID 34270462, 2021).
endometrial cancer (6 papers, 2019 to 2022). Primary or metastatic malignant neoplasm involving the endometrium (mucous membrane that lines the endometrial cavity). "Observed positive correlation between mRNA levels of TGFβ1 and TGFβ1-induced expression of FXYD5/dysadherin is associated with pronounced invasive phenotype of endometrial cancer, depicted by myometrial invasion > 50%, grade 3, and intermediate/high risk of recurrence." (PMID 34501347, 2021). "Besides, a study demonstrated that FXYD5/Dys could serve as a biomarker of endometrial cancer progression associated with TGF-β1 and NF-κB signaling pathways." (PMID 32596316, 2020). "FXYD5 was found to be upregulated in endometrial cancer, and patients with high tumor grades tended to have higher expression levels of FXYD5." (PMID 34270462, 2021). "In line, TGF-β treatment induced FXYD5 expression in endometrial cancer, which in turn led to activation of NF-κβ pathway." (PMID 34059618, 2021). "In endometrial cancer, FXYD5 was also reported to be a potential biomarker related to the TGF-β1 and NF-κB pathways, resulting in tumor dissemination." (PMID 34270462, 2021). "Furthermore, analysis of the cancer genome atlas RNAseq data revealed a correlation between transcriptional activation of NF-κB p65-regulated genes with FXYD5/dysadherin mRNA levels in endometrial cancer, which is stronger expressed in higher staged or invasive ECs." (PMID 35328833, 2022).
glioblastoma (3 papers, 2016 to 2022). The most malignant astrocytic tumor (WHO grade IV). "FXYD5 is a transmembrane auxiliary subunit of the Na+-K+-ATPase; it shows a 2.5-fold increase in glioblastoma." (PMID 27716384, 2016). "Within the shadowed columns, glioblastoma appears to have the highest number of modified ion-channel genes (namely: FXYD5, KCNE3, KCNE4, CLIC1, TRPM3)." (PMID 27716384, 2016). "In primary glioblastoma cases, M1 macrophages were classified by CIBERSORT as monocyte-derived tumor-associated macrophages (Mo-TAMs), based on the expression of genes such as TGFB1, CLEC12A, and FXYD5." (PMID 35203505, 2022).
cystic fibrosis (2 papers, 2016 to 2024). Autosomal recessive disorder caused by pathogenic variants in the CFTR gene (cystic fibrosis transmembrane conductance regulator), which encodes a chloride and bicarbonate channel expressed in epithelial cells, and follow the diagnosis criteria. "Further, we identified an up-regulation in two EndoMT-related genes in Rtn3-null ENs: Sox17, a developmental transcription factor linked to endothelial-to-fibroblast conversion, and Fxyd5, associated with cystic fibrosis airway epithelia." (PMID 38937317, 2024). "A significant increase in FXYD5 was found also in the lungs and nasal epithelium of cystic fibrosis mice, at the level of both protein and mRNA, and this up-regulation was directly correlated with loss of Cystic fibrosis transmembrane conductance regulator (CFTR) function." (PMID 27066483, 2016).
liver cancer (2 papers, 2019 to 2023). An epithelial or non-epithelial malignant neoplasm that arises from the liver. "In the same study, FXYD5/Dys overexpression in liver cancer cell lines was found associated with decreased E-cadherin protein levels and decreased Ca2+-dependent cellular aggregation." (PMID 31867269, 2019).
melanoma (2 papers, 2011 to 2016). A malignant, usually aggressive tumor composed of atypical, neoplastic melanocytes. "Melanoma cells were surface stained for TSPAN8, RELN and FXYD5 or intracellularly stained for renalase, CAPG, BCL11A and ID3." (PMID 21081927, 2011).
renal carcinoma (2 papers, 2019 to 2022). A carcinoma arising from the epithelium of the renal parenchyma or the renal pelvis. "Taking into account results presented in the previous section and that modulation of FXYD5/Dys expression has been associated with an aggressive cellular behavior in breast and renal cancer cellular models, the impact of its knockdown upon cell behavior was evaluated." (PMID 31867269, 2019). "In addition, other E-cadherin-independent mechanisms have been proposed; in particular, an association has been found between FXYD5/Dys expression, nuclear factor (NF)-κB pathway activation, and CCL-2 (NF-κB target gene) upregulation in breast and renal cancer cell lines." (PMID 31867269, 2019).
serous ovarian carcinoma (2 papers, 2019 to 2020). "Furthermore, high-grade serous ovarian carcinoma patients with higher expression of FXYD5 owned a shorter survival time than patients with lower expression of FXYD5, and FXYD5 played a critical role in survival and prognosis of HCSOC." (PMID 32596316, 2020).
acute pancreatitis (1 paper, 2022). An acute inflammatory process that leads to necrosis of the pancreatic parenchyma. "Besides, it was noted that FXYD5 was significantly upregulated in pancreatic tissue of mice with acute pancreatitis, which indicated that FXYD5 directly participated in the occurrence of acute pancreatitis." (PMID 35042436, 2022). "Although FXYD5 has been investigated in many diseases, its role in acute pancreatitis is unknown, especially its effects on the inflammatory response of acute pancreatitis." (PMID 35042436, 2022). "The results showed that FXYD5 was upregulated in acute pancreatitis and FXYD5 silence could promote the growth but suppress the inflammatory response of cerulein-induced AR42J cells." (PMID 35042436, 2022). "In view of this, we wondered whether FXYD5 downregulation could inhibit the inflammatory response in acute pancreatitis via regulating JAK2/STAT3 pathway." (PMID 35042436, 2022).
cholangiocarcinoma (1 paper, 2014). A carcinoma that arises from the intrahepatic biliary tree (intrahepatic cholangiocarcinoma) or from the junction, or adjacent to the junction, of the right and left hepatic ducts (hilar cholangiocarcinoma). "For instance, FXYD2 is differentially expressed in cholangiocarcinoma cells, as is FXYD5 in epithelioid sarcoma, head and neck squamous cell carcinoma, small cell carcinoma, pancreatic cancer cells and breast cancer cells." (PMID 25013464, 2014).
endometriosis (1 paper, 2025). The growth of functional endometrial tissue in anatomic sites outside the uterine body. "Immunohistochemical analysis identified FXYD5 as a marker gene specifically overexpressed in the dStromal late cell subtype of endometriosis." (PMID 40757199, 2025). "In the dStromal-late mesenchymal cell subtype, FXYD5 was specifically localized to stromal cells of endometriotic lesions and showed markedly higher expression (p = 0.02) in endometriosis tissues compared to control tissues, again confirming our previous analytical results." (PMID 40757199, 2025).
glomerulonephritis (1 paper, 2021). A renal disorder characterized by damage in the glomeruli. "In our data, we found FXYD5 was enriched in podocyte of glomerulonephritis, which needs further study to declare the role of FXYD5 within podocyte in the progression of glomerulonephritis." (PMID 33754492, 2021). "Furthermore, in the cluster of the podocyte, three glomerulonephritis related genes named FXYD5, CD74 and B2M were found." (PMID 33754492, 2021).
head and neck cancer (1 paper, 2021). A primary or metastatic malignant neoplasm affecting the head and neck. "Studies revealed that patients with high FXYD5 expression might benefit less from RT compared to these with low FXYD expression in head and neck cancer." (PMID 34270462, 2021).
hearing loss (1 paper, 2019). "This study is the largest GWAS meta-analysis of ARHI to date and identified 7 associated loci, of which 5 are novel (FXYD5, IPP, SPIRE2, SPTBN1 and TRIL) and 2 have been previously related to hearing loss (ILDR1, ISG20)." (PMID 31645637, 2019).
heart failure (1 paper, 2025). Inability of the heart to pump blood at an adequate rate to meet tissue metabolic requirements. "Several members of the FXYD family have been linked to major human diseases, including heart failure (FXYD1), hypomagnesemia (FXYD2), cancer (FXYD3, FXYD5), and schizophrenia (FXYD6), making them attractive specific targets for future therapies." (PMID 40428357, 2025).
hepatocellular carcinoma (1 paper, 2021). A malignant tumor that arises from hepatocytes. "In hepatocellular carcinoma FXYD5 expression was linked to stem cell like properties, decreased apoptosis and higher tumour initiation in mice." (PMID 34059618, 2021).
intestinal tumor (1 paper, 2022). "Consistently, p-FAK was elevated in dysadherin-positive cells within the intestinal tumors of ApcMin/+/Fxyd5+/+ mice and this increase in p-FAK was significantly decreased by dysadherin deletion." (PMID 35673579, 2022). "The complete absence of dysadherin expression in the intestinal tumor epithelium of ApcMin/+;Fxyd5-/- mice was confirmed." (PMID 35673579, 2022). "Conversely, when we explored the stromal effect of dysadherin depletion on tumorigenesis by inoculating murine intestinal tumor cells (MC38) 27 into Fxyd5+/+ and Fxyd5-/- mice, we found that dysadherin-KO physiological environment did not affect tumor seeding and growth." (PMID 35673579, 2022).
metastatic tumors (1 paper, 2022). "Many studies have testified that FXYD5 was upregulated in metastatic tumors, which suggested that FXYD5 acted as an oncogenic marker." (PMID 35042436, 2022).
non-small cell lung carcinoma (1 paper, 2021). A group of at least three distinct histological types of lung cancer, including non-small cell squamous cell carcinoma, adenocarcinoma, and large cell carcinoma. "FXYD5 may be an independent predictor of survival for patients with non-small cell lung cancer." (PMID 34270462, 2021).
pancreatic ductal adenocarcinoma (1 paper, 2014). An infiltrating adenocarcinoma that arises from the epithelial cells of the pancreas. "FXYD5 overexpression in pancreatic ductal adenocarcinoma reflects tumor aggressiveness and promotes metastasis." (PMID 24979261, 2014).
spinal cord injuries (1 paper, 2023). "Persons with spinal cord injuries express muscle FXYD5 at >10-fold higher levels than healthy comparators, which implies that muscle activation regulates FXYD5 expression." (PMID 36982661, 2023).
tongue cancer (1 paper, 2021). A malignant neoplasm affecting the tongue. "Importantly, reducing the membrane FXYD5 expression as such, the tongue cancer cell-cell adhesion increases with subsequent remarkable reduction in mobility." (PMID 34059618, 2021). "As FXYD5 serves as a marker of worse prognosis in multitude of cancers, including OTSCC, our results suggest it as a promising therapeutic target also for tongue cancer." (PMID 34059618, 2021). "The effects of FXYD5 silencing on OTSCC function was confirmed and re-producible in another aggressive tongue carcinoma cell line, SCC-25, which showed dramatic decrease in migration but also a significant effect on proliferation and clonogenicity." (PMID 34059618, 2021).